MTOR (mechanistic target of rapamycin kinase)
Diseases named in the same sentence as MTOR in open-access papers (continued):
Sharing a sentence is not in itself a finding about the gene and the disease.
tumor (continued). "Metformin was also effective in reducing the growth of intestinal polyps in tumor suppressor Apc-mutant mice by reducing mTOR/S6K/S6 signaling in the epithelium of the intestine." (PMID 35574410, 2022). "Altered metabolic pathways, especially mTOR pathway in tumors play key roles in tumor growth and immnosuppressive acidic tumor environment." (PMID 36203437, 2022). "Many of these, like mTOR and cMyc are reported to contribute to tumor progression and aggressive behavior." (PMID 35054064, 2022). "In recent years, targeted intervention in signal pathways, such as RAGE-PI3K/AKT/mTOR and RAGE-AMPK/mTOR has provided new ideas for treating tumor diseases." (PMID 35956875, 2022). "Blocking of PGAM1 suppresses mTOR-mediated tumor growth, and PGAM1 abundance is an unfavorable predictor in patient survival." (PMID 35810157, 2022). "Studies have shown that the THSD7A acts via the TGF-β (common in non-tumor diseases) or mTOR signaling pathways (common in tumor diseases)." (PMID 36506585, 2022). "Since M1 macrophages have cytotoxic activity on cancer cells, the HIF-1α/miR-30c/REDD1/mTOR axis was suggested as a mechanism for hypoxia-induced suppression of anti-tumor immunity in GC." (PMID 35681691, 2022). "Constitutive activation of oncogenic pathways such as the Akt/mammalian target of rapamycin (mTOR) pathway in tumor cells has also been reported to lead to increased glycolysis and elevated uptake of extracellular glucose." (PMID 34275008, 2022). "At the same time, the synthesis of kinases, including AKT, phosphoinositide 3-kinase (PI3K), ERK, STAT3, and the mammalian target of rapamycin (mTOR), were significantly reduced in both tumor cell types when co-cultivated with MSCs." (PMID 35741334, 2022). "The results thus underscored the importance of mTOR-mediated protein synthesis pathway in the induction of Bcl6 in tumor-conditioned macrophages." (PMID 36542153, 2022). "It binds the ATP-binding pocket of the p110 subunit of PI3K and to the catalytic site of mTOR, so it is able to inhibit both mTORC complexes (mTORC1 and mTORC2), resulting in effective inhibition of tumor proliferation and growth." (PMID 36496978, 2022). "For instance, deregulated activation of protein kinases and phosphatases, e.g., ErbB2, EGFR, MAPK, VEGF, mTOR, have become one of the most widely studied tumor therapeutic targets." (PMID 36497095, 2022). "When tumor grew to an average size around 50-100mm3, mice were randomized into four groups treated with pyrotinib 40 mg/kg, HDACs/mTOR inhibitor 1 10 mg/kg or combined with same dosages of vehicle." (PMID 36457011, 2022). "Downregulation of Mcl-1 upon mTOR inhibition was accompanied by a reduction in tumor volume, which was further reduced upon co-treatment with the Bcl-2/Bcl-xL inhibitor ABT-263." (PMID 35053443, 2022). "The results from orthotopic mouse model also validated that FOXH1 promoted HA22T tumor growth via triggering mTOR activation." (PMID 35255005, 2022). "Metformin combined with cisplatin inhibits tumor cell angiogenesis, growth, proliferation, and survival via the mTOR/AKT pathway." (PMID 36397350, 2022). "Targeting PI3K/Akt/mTOR pathway not only elicits apoptosis to inhibit tumor cell proliferation but also triggers autophagy." (PMID 36104717, 2022). "DPYSL2 is related to the mTOR signaling pathway; mTOR, as a central regulator of proliferation signal transduction, is an ideal target for tumor treatment." (PMID 35051904, 2022). "Adipocyte-derived leptin and IL-6 play key roles in the activation of the Jak/STAT and PI3K/Akt/mTOR pathways, which are frequently dysregulated in tumor pathogenesis." (PMID 35805003, 2022). "In conclusion, periostin activates the proliferation and migration of tumor cells by the ILK/AKT/mTOR pathway." (PMID 35676936, 2022). "MIR-494 reduces PTEN expression in MDSCs, subsequently activating AKT, NF-κB, and mammalian target of rapamycin (mTOR) which, in turn, potentiate their immunosuppressive function, thereby supporting tumor growth." (PMID 36010994, 2022).
tumor (continued). "Previous studies have revealed that the PI3K/AKT/mTOR signaling pathway plays a critical role in tumor progression through regulating cell proliferation, apoptosis and chemoresistance." (PMID 36151545, 2022). "Activation of protein kinase B, which is part of the PI3K/Akt/mTOR pathway, can promote tumor proliferation and malignancy and is directly related to malignant cell chemoresistance mediated by MDR1 expression." (PMID 36297616, 2022). "•The essential amino acids activate the mitochondrial BCAA oxidation and ER stress, inhibiting glycolysis and mTOR signalling in tumour cells." (PMID 35367410, 2022). "The IHC staining of subcutaneous tumour tissues revealed decreased p-mTOR and increased DDIT4 levels in the sh-DDIT4-AS1 group compared with the shCtrl group." (PMID 36056355, 2022). "An mTOR inhibitor, AY-22989, attenuated the activation of the PI3K/AKT/mTOR pathway and suppressed the tumor malignant capabilities induced by LHPP knockdown." (PMID 36484014, 2022). "Drugs under investigation mainly act on the MAPK/ERK and PI3K/AKT/mTOR pathways, tumor microenvironment, or aberrantly over-expressed cell surface receptors." (PMID 35291225, 2022). "The activity of T cells is inhibited, leading to immune escaping of tumor cells through phosphatidylinositol 3-kinase (PI3K)/AKT serine/threonine kinase 1 (AKT)/mammalian target of rapamycin (mTOR) and other signaling pathways." (PMID 35223466, 2022). "Suppressing the expression of PIK3R5 by miRNAs resulted in the promotion of epithelial-mesenchymal transition and oncogenic autophagy by regulating the Akt-mTOR signaling pathway in tumor cells." (PMID 35884407, 2022). "As an oncogenic signaling pathway, direct inhibition of the mTOR axis regulates the metabolic characteristics of tumor-infiltrating immune cells and blocks the malignant phenotype of cells." (PMID 36200045, 2022). "Targeting the mTOR pathway with the dual mTORC1/2 inhibitor TAK-228 slows tumor growth and extends survival in mice bearing orthotopic xenografts." (PMID 35484114, 2022). "In GBM, the impressive overactivation of mTOR, which suppresses autophagy, plays a mechanistic role in tumor progression." (PMID 35326535, 2022). "Western blotting was performed to evaluate the activities of the PI3K/AKT/mTOR signaling pathway both in cells and tumor tissues." (PMID 36132221, 2022). "In contrast, USP22 can exert tumor‐suppressive functions in CRC, such that its loss increases CRC burden by modulating mTOR activity." (PMID 34743406, 2022). "For example, PD-L1 in tumor cells can activate the PI3K-Akt-mTOR pathway, stimulate glycolysis, and enhance glucose uptake by the tumor cells." (PMID 35468826, 2022). "In NSCLC, an autocrine feed-forward loop has been discovered in which tumor-derived VEGF stimulates an increase in VEGF production via VEGFR-2-dependent activation of the mTOR pathway, substantially amplifying the initial proangiogenic signal." (PMID 35626731, 2022). "Combined with the results of Western blotting, compound 3h exerted anti-tumor effects in LNCaP cells by inhibiting glycolysis, and inducing apoptosis and autophagy mediated by the Akt/mTOR signaling pathway." (PMID 36612260, 2022). "This group of compounds showed particularly high efficacy on the activity of PI3Kα and mTOR enzymes and had excellent efficacy in tumour cell proliferation tests." (PMID 35614940, 2022). "mTOR-I blocks mTOR and leads to reduced lymphocytes, endothelial cells, tumor cells, and cytomegalovirus." (PMID 35265364, 2022). "It has been shown that the mTOR pathway is closely related to tumor proliferation, invasion, and metastasis." (PMID 34675984, 2021). "Given that CAF paracrine signaling modulated GIST biology, we directly targeted CAFs with a dual PI3K/mTOR inhibitor, which synergized with imatinib to increase tumor cell killing and in vivo disease response." (PMID 33603171, 2021).
tumor (continued). "Considering the fact that tumor proliferation and mTOR signaling were more active in the low score group, it was more reasonable than the high score group to be more sensitive to Sunitinib." (PMID 34055790, 2021). "mTOR, the essential kinase of both mTORC1 and mTORC2 complexes, is targeted for ubiquitinylation and degradation by binding to the tumor suppressor FBXW744." (PMID 34290272, 2021). "In this study, along with the reduction of cell viability in vitro and tumor growth in vivo, the signaling transduction of IGF-1 R/p-PI3K/p-AKT/p-mTOR was abolished in ropivacaine-treated HepG2 cells and ropivacaine-challenged tumor-bearing mice in vivo." (PMID 34696683, 2021). "In our case, genetic alteration in the TSC2 gene was identified in tumor cells, so an mTOR inhibitor was started after the second relapse." (PMID 34542724, 2021). "The positive correlation between Vp (meanvalue, Q75, Q90, Q95) and mTOR in SCLC also indicated that the activation of downstream signal molecules of this signal pathway increased tumor blood supply." (PMID 33865336, 2021). "PF338 tumor cells harbored mutations in PIK3CA and PTEN and were sensitive to dual PI3K/mTOR inhibition." (PMID 34257602, 2021). "The AKT/mTOR signaling pathway mediates tumor metabolic homeostasis and can promote tumor growth and metastasis." (PMID 35070996, 2021). "Our former data reveal that the tumor-promoting protein HMGB1 was involved in regulation of autophagy via AMPK/mTOR signaling and verified anti-HCC effects of HMGB1 inhibition accounted for autophagy induction." (PMID 33747917, 2021). "Torin1 alone or in combination significantly decreased downstream mTOR activity, as measured by the ratio of phosphorylation of rpS6 relative to total rpS6 within the tumor samples." (PMID 34031411, 2021). "Consistently, silencing FATP5 led to decreased AMPK activity and enhanced mTOR-S6K signaling in tumor samples, while stimulating the AMPK pathway by metformin treatment reversed these changes." (PMID 34772914, 2021). "In the presence of neoplasms, this pathway is incorrectly regulated, as there is an increase in the activation of the TOR complex (mTOR) by mutations of function gain in oncogenes and loss of tumor suppressor genes." (PMID 33668689, 2021). "Another mTOR inhibitor, everolimus, has been found to produce direct anti-tumor effects through cell cycle arrest and increased apoptosis as well as anti-angiogenic activity in preclinical models." (PMID 34361836, 2021). "Our data further demonstrated that circRHOBTB3 acts as a miRNA-sponge to maintain the expression level of miR-600-targeted gene NACC1, thereby increasing autophagic flux of PDAC cells for adaptation of tumor development through inhibiting Akt/mTOR pathway." (PMID 34416910, 2021). "In vitro studies in lymphoma, leukemia, glioblastoma, colorectal cancer have shown ONC201 increases apoptosis and inhibits AKT/mTOR signaling, leading to a corresponding decrease in tumor growth in mouse models." (PMID 33557912, 2021). "One of the most interesting anti-tumor effects of metformin regards the disruption of intracellular signaling mediated by the mammalian target of rapamycin (mTOR)." (PMID 35008275, 2021). "Ce6 was the selected photosensitizer and NVP-BEZ235 was used due to its ability to inhibit the PI3K/AKT/mTOR pathway that is related to tumor progression and proliferation and inhibit the repair of DNA damage in tumor cells." (PMID 34835896, 2021). "Another study showed that ridaforolimus inhibits mTOR activity, and thus also tumor cell proliferation and VEGF production." (PMID 34361836, 2021). "Han found that daucosterol can inhibit tumor growth by affecting the PI3K-Akt-mTOR signaling pathway." (PMID 34484411, 2021). "IGF1R/IGF interaction activates Raf/MEK/ERK and P13K/AKT/mTOR signaling pathways, which are critical processes during tumor progression." (PMID 33827418, 2021).
tumor (continued). "Met decreases the phosphorylation of phosphoinositide 3-kinase and Akt, which in turn inhibits the mTOR signaling pathway, suppresses abnormal proliferation, and reduces the apoptosis tolerance of tumor cells." (PMID 34659521, 2021). "The PI3K-Akt-mTOR signaling cascade is frequently activated in PCa, and promotes tumor growth by mediating a plethora of cellular processes." (PMID 34679526, 2021). "ISL regulated the expression of Bcl-2, the mTOR pathway, and the expression of other related proteins, triggering apoptosis and autophagy in drug-resistant tumor cells, while the inhibition of autophagy enhanced ISL-mediated drug-resistant cell death." (PMID 33494431, 2021). "The results indicated that ethyl ferulate treatment reduced patient-derived esophageal xenograft tumor growth by inhibiting the mTOR/AKT/p70S6K signaling pathway." (PMID 35155187, 2021). "In situ metabolic phenotyping in recent studies highlights the importance of metabolic plasticity, mTOR hyperactivity, and their role in tumor progression." (PMID 35029792, 2021). "Temsirolimus and everolimus are two FDA-approved drugs that exert anti-tumor effects through mTOR pathway inhibition." (PMID 33996789, 2021). "AKT/mTOR signaling pathway is widely involved in the origin and development of solid tumors and plays a key role in the proliferation and apoptosis of tumor cells." (PMID 34514167, 2021). "CDX-3379 decreased tumor pS6 staining (surrogate for mTOR activity), and tumor cell proliferation as measured by BrdU staining." (PMID 33888713, 2021). "The mTOR signaling pathway plays a central role in cell proliferation and metabolism and is involved in tumor initiation and progression." (PMID 33946531, 2021). "Further, knockdown of MLST8 suppresses tumor growth by inhibiting MTOR complex formation and activity." (PMID 34529665, 2021). "FUS-mediated circRHOBTB3 functions as a tumor activator to promote PDAC cell proliferation by modulating miR-600/NACC1/Akt/mTOR axis regulated autophagy." (PMID 34416910, 2021). "We generated an mTOR-driven HCC mouse model, by liver-specific deletion of the tumor suppressors Pten and Tsc1, to investigate the molecular and cellular mechanisms of mTOR-driven tumorgenicity." (PMID 34348664, 2021). "Altogether, these results underscore the critical role played by the oncogenic mTOR pathway in TNBC tumor development." (PMID 34031411, 2021). "UBE2O promoted the migration, invasion, and proliferation of tumor cells by activating the AMPKα2/mTOR pathway in HCC." (PMID 34790050, 2021). "Compounds 40c, 40m, and 40n revealed potent anti-tumor activity in vitro by decreasing the mTOR or PKB level, with IC50 values less than 5 μM on K562 cells." (PMID 33801899, 2021). "For instance, the findings of some studies revealed that miR-99a-5p exhibited a tumor suppressor role via targeting mTOR in BC." (PMID 34660642, 2021). "Temsirolimus is a potent inhibitor of the mechanistic target of rapamycin (mTOR) pathway, a key regulator of tumor hypoxia and inducer of several pro-angiogenic growth factors, including VEGF." (PMID 34077449, 2021). "Inhibition of the PI3K/AKT/mTOR axis, which is often deregulated in this tumor, is considered a potentially valuable therapeutic strategy." (PMID 34680108, 2021). "AKT/mTOR is a signaling pathway that regulates proliferation, apoptosis, and the distribution of the cell cycle in tumor cells, and the excessive activation of this signaling pathway promotes radioresistance in various tumors." (PMID 34224316, 2021). "The AIM2 inflammasome can inhibit HCC tumor growth by targeting the mTOR signal and inducing pyroptosis." (PMID 34820372, 2021). "Our study shows that mTOR inhibition in the tumor microenvironment can attenuate the interaction between tumor cells and macrophages during radiotherapy." (PMID 33959512, 2021). "In the current investigation, we assessed the value of selected members of the PI3K/mTOR/AKT pathway to serve as tumor markers or therapeutic targets for this disease." (PMID 34066040, 2021).
tumor (continued). "In endometrial tumors, aberrant activation of the NOTCH cascade has been associated with increased cell proliferation, and suppression of the mTOR pathway has been found to repress tumor initiation and progression." (PMID 33822486, 2021). "The uses of a combination of mTOR inhibitors with other pathway inhibitors are under investigation in different tumor types." (PMID 33802643, 2021). "In an attempt to predict the response to mTOR inhibitors, an interesting study showed that the level of phosphorylated S6 ribosomal protein expression, reflecting the mTOR pathway activation, was predictive of early tumor response to the drug." (PMID 34680376, 2021). "In NSCLC, second and third-generation EGFR-TK inhibitors were prepared for tumor cells with the T790M gatekeeper mutation and PI3K/AKT/mTOR inhibitors were under clinical trials." (PMID 34681198, 2021). "Rapamycin can inhibit the activity of mechanistic target of rapamycin (mTOR), decrease proliferation of T lymphocytes to reduce adipogenesis and enhance lipogenesis and induce tumor immune evasion." (PMID 34174965, 2021). "As reported in various literature, Akt/mTOR pathway is a common pathway regulating PDAC tumor progression, and acts as an inhibitory role in autophagy response." (PMID 34416910, 2021). "Activated mTOR stimulates translation and inhibits autophagy, and lower mTOR activity decreases tumor incidence in animal models." (PMID 34330319, 2021). "Enhanced glycolysis in tumors in enough to override the protective role of T cells to control tumor growth, and blocking PD-L1 decreases glycolysis by inhibiting mTOR activity and reduces expression of glycolysis enzymes." (PMID 33807260, 2021). "By inhibiting mTOR, Evr affects tumor cell metabolism and regulates tumor cell resistance, but its mechanism of action needs to be further investigated." (PMID 33849427, 2021). "Subsequent studies showed that Salmonella can also inhibit tumor angiogenesis through AKT/mTOR pathway by suppressing the levels of HIF-1α and VEGF." (PMID 33717106, 2021). "The uptake of glutamine mediated by ASCT2, followed by its rapid efflux via LAT1 in exchange for EAAs such as leucine, is the rate-limiting step for mTOR signaling activation in tumor cells." (PMID 33401672, 2021). "Prior studies have identified several anti-tumor mechanisms of metformin with adenosine monophosphate-activated protein kinase (AMPK)-dependent PI3K/Akt/mTOR pathway inhibition considered as an important direct mechanism of metformin in treating EC." (PMID 34134781, 2021). "Both hyperactivation of the PI3K/AKT/mTOR and JAK/STAT signaling pathways, for example, are associated with poor prognosis and MM tumor proliferation, and are actively being explored in preclinical drug research as potential drug targets." (PMID 34884535, 2021). "It is believed that the activated mTOR supports certain tumor cell growth by promoting protein synthesis, which is also the most important function of mTOR signaling." (PMID 34977014, 2021). "A significant difference in p-mTOR expression was observed between the tumor and normal tissues (χ2 = 5.492, P = 0.019)." (PMID 34221974, 2021). "The PI3K/Akt/mTOR pathway is not only involved in the regulation of the proliferation and apoptosis of cancer cells but also promotes normal and tumour angiogenesis." (PMID 34439105, 2021). "Further, the potential of PL in inhibiting tumor formation was attributed to the inhibition of the Ras/PI3K/Akt/mTOR signaling pathway." (PMID 36046754, 2021). "Proper activation of the mTOR pathway increases the expression of oncogenes, and pathway inhibition may cause downregulation of certain oncogenes' expression levels, and at the same time activate other oncogenes through the cross-talk pathway to cause tumor progression." (PMID 34194607, 2021).